PON1 (paraoxonase 1)
Diseases named in the same sentence as PON1 in open-access papers (continued):
Sharing a sentence is not in itself a finding about the gene and the disease.
Insulin resistance (32 papers, 2012 to 2026). Increased resistance towards insulin, that is, diminished effectiveness of insulin in reducing blood glucose levels. "In the PON1 gene locus, Met-Leu 54 polymorphism is associated with insulin resistance in healthy persons and is strongly LD with the PON1 192 polymorphism." (PMID 35627115, 2022). "Previous studies have consistently reported that PON1 is a marker of cardiovascular risk in youth with type 1 diabetes and that Q192R polymorphism of PON 1 gene is associated with insulin resistance." (PMID 25964115, 2015). "Fructose consumption in dietary conditions of magnesium deficiency induces insulin resistance while lowering PON1 gene activity." (PMID 33889422, 2015). "Results from previous studies in which decreased PON1 activity and concentration has been linked with impaired glucose tolerance and increased insulin resistance in healthy subjects also support this hypothesis." (PMID 25551104, 2014). "The effects on glucose metabolism have been studied, finding that PON1 affects insulin sensitivity and glucose tolerance, and that the abnormal PON1 function leads to insulin resistance." (PMID 38474211, 2024). "The authors explained their findings by a possible predisposition of individuals with low-expressor genotypes to insulin resistance or the linkage of PON1 promoter region variations with another gene involved in glucose control." (PMID 33670025, 2021). "Reduced PON-1 activity and concentration in studies of healthy subjects with elevated fasting glucose levels and increased insulin resistance support these in vitro data." (PMID 26800892, 2016). "While it is unclear how decreased PON1 activity contributes to the development of T2D, there is evidence to suggest that inorganic mercury exposure plays a role in insulin resistance." (PMID 33889422, 2015). "Its consumption by humans can result in dietary mercury exposure, and insulin resistance and reduced PON1 gene activity in rats." (PMID 33889422, 2015). "It is suggested that oxidative stress induced by reduced PON1 concentration and/or activity results in reducing glucose uptake from blood by muscle cells and develops into insulin resistance." (PMID 25551104, 2014). "Once rats fed a high dose of fructose are considered a nutritional model for insulin resistance, the present study investigated the effects of a high-salt diet in fructose-fed insulin-resistant rats on PON1 and its influence in serum and oxidative parameters." (PMID 22738670, 2012). "Thus, this study aimed to analyze the relationship between serum levels of oxidized lipoproteins and diet, lipid profiles, and MPO and PON1 levels in young subjects with insulin resistance." (PMID 39599716, 2024). "We hypothesized that young subjects with insulin resistance have high levels of oxidized LDL and HDL associated with a high-fat diet, high myeloperoxidase levels, and a low PON1 concentration." (PMID 39599716, 2024). "A positive correlation between the PON1 activity and insulin resistance was shown." (PMID 31781329, 2019). "In addition, our in silico analysis identified several key metabolic and cardiovascular pathways related to PON1, including AGE-RAGE signaling, lipid metabolism, and insulin resistance." (PMID 39857440, 2025). "Improved glucose, HbA1c, insulin, insulin resistance, CRP, antioxidant capacity, PON-1." (PMID 40733199, 2025). "When insulin resistance occurs, first there are no significant changes in PON1, showing the importance of an early diagnosis and of lifestyle changes and treatment in the first phase." (PMID 38474211, 2024). "Suppression of CEACAM1, GLUT2, and PON1, and elevation of CD36, PCK1, and G6PK were also found to be characteristic in hyperglycemic HepG2 cells compared with normoglycemic cells, suggesting insulin resistance and NAFLD." (PMID 31805072, 2019).
Insulin resistance (continued). "In conclusion, this is the first study in the literature, as far as the authors know, which simultaneously evaluates epicardial adipose tissue thickness and oxidative stress parameters, the levels of paraoxonase-1, arylesterase, hs-CRP, and insulin resistance in a patient population with MeS." (PMID 25530760, 2014). "However, PON1 counteracts insulin resistance, not using the insulin receptor, but acting through an enhanced expression of the PI3K/Akt signaling pathway." (PMID 36290747, 2022).
breast carcinoma (31 papers, 2007 to 2025). "For the first time, our study analyzed the association of heart damage with the PON1 rs3735590 polymorphism in patients with breast cancer treated with doxorubicin." (PMID 40362292, 2025). "PON1 dysregulation was associated with a variety of cancers including breast cancer, pancreatic cancer, endometrial Cancer, and colorectal cancer." (PMID 38374122, 2024). "Subgroup analysis by ethnicity revealed that PON1 rs854560 polymorphism was a significantly associated with breast cancer among Asian and Caucasian women." (PMID 34452542, 2021). "For example, PON1 gene polymorphism has been associated with breast cancer susceptibility, while PON1 concentration has been positively correlated with the degree of bone destruction in multiple myeloma." (PMID 34819088, 2021). "To date, several variants within PON1 gene associated with susceptibility to breast cancer have been verified." (PMID 34452542, 2021). "Our pooled data revealed that the PON1 rs662 and rs854560 polymorphisms were significantly associated with an increased risk of breast cancer in the overall population." (PMID 34452542, 2021). "This study aimed to investigate the association of PON1-L55M functional polymorphism with breast cancer risk." (PMID 31983193, 2020). "The role of paraoxonase 1 (PON1) in detoxification of cancer-causing oxidative stress encourages scientists to evaluate PON1 gene variations in susceptibility to breast cancer." (PMID 31983193, 2020). "This study aimed to investigate the association of PON1-L55M genetic polymorphism with breast cancer susceptibility in a case-control trial." (PMID 31983193, 2020). "Recent studies have shown that low PON1 activity is associated with increased risk of breast cancer 18 and risk of gastric cancer metastasis." (PMID 33046970, 2020). "In conclusion, PON1-Q192R allele decreased the cancer risk especially breast cancer; there was an association between PON1-L55M allele and increased overall cancer risk." (PMID 31467900, 2019). "In conclusion, our study has demonstrated that PON1-Q192R can significantly reduce the risk of cancer and the polymorphism of PON1-L55M is a risk factor leading to cancer, especially breast cancer." (PMID 31467900, 2019). "One meta-analysis about PON1 genetic polymorphisms and breast cancer susceptibility has concluded that the presence of a R allele on the polymorphism Q192R was associated with a decreased risk of breast cancer." (PMID 31430977, 2019). "For PON1-Q192R polymorphisms, in the stratified analyses by cancer type, PON1-Q192R allele was associated with reduced cancer risks in breast cancer." (PMID 31467900, 2019). "Genotype frequencies (%) of the analyzed PON1 gene polymorphisms in patients with breast cancer and in the control group of subjects." (PMID 29176871, 2017). "Linear regression analyses of the variables independently associated with PON1 activity and concentration in breast cancer patients and the control group of subjects." (PMID 29176871, 2017). "In this study, we explored associations between paraoxonase 1 (PON1) L55M and Q192R gene polymorphisms and the risk of breast cancer in 365 female breast cancer patients and 378 healthy controls from the Guangxi region of southern China." (PMID 28445984, 2017). "Low PON1 activity is also associated with breast cancer mortality and certain genotypes of PON1 gene with lung carcinoma." (PMID 24665146, 2014). "The association between polymorphism of obesity-related genes (LEP, LEPR and PON1) and breast cancer risk has been investigated." (PMID 23826274, 2013). "Our results suggest that the PON1-L55M genetic variation could be a genetic risk factor for breast cancer risk and it could be considered as a molecular biomarker for screening of susceptible women." (PMID 31983193, 2020).
breast carcinoma (continued). "Our data revealed that there are significant associations between PON1-L55M polymorphism and breast cancer risk in homozygote (OR= 2.13, 95%CI= 1.14-4.00, p= 0.018), dominant (OR= 1.72, 95%CI= 1.07-2.76, p= 0.024), and allelic (OR= 1.55, 95%CI= 1.12-2.15, p= 0.008) models." (PMID 31983193, 2020). "Our findings suggest that the PON1-L55M polymorphism is a genetic risk factor for breast cancer risk and it could be considered as a possible molecular biomarker for screening of susceptible women." (PMID 31983193, 2020). "Next, we need a larger sample size at protein levels to confirm whether PON1 polymorphisms may be potential genetic markers of tumor prognosis and identify its role in the risk of women developing breast cancer." (PMID 31467900, 2019). "In addition, not only genetic factors but also other contributors including nutrition and lifestyle can significantly affect PON1 enzyme activity, thereby reducing the risk of breast cancer." (PMID 31467900, 2019). "In fact, individuals with MM and QQ genotypes present lower levels of PON1, which may decrease the ability to detoxify inflammatory oxidants, as well as dietary carcinogens, leading to an increased risk of breast cancer development." (PMID 31430977, 2019). "For instance, PON1-L55M polymorphism may increase the risk in multiple cancer types, such as prostate and breast cancers but decrease renal cell carcinoma and ovarian cancer risk." (PMID 31467900, 2019). "Moreover, in the stratified analyses by cancer type, polymorphism of PON1-L55M played a risk factor in the occurrence of breast cancer, hematologic cancer, and prostate cancer." (PMID 31467900, 2019). "In addition, decreased homozygote Q allelic PON1 activity has been observed in breast cancers while M and Q alleles of PON1 have been regarded as high susceptibility risk factors." (PMID 28467805, 2017). "Liu and coworkers suggested that the LEPR Q223R polymorphism might be implicated in the development of breast cancer in East Asians and PON1 L55M might increase breast cancer risk." (PMID 23826274, 2013). "Further studies would also be essential to determine the cut-off value of PON1 activity, predicting the risk of PCa recurrence after RT and the possible relation of PON1 concentration with the risk of recurrence, especially since such relations were reported for lung and breast cancers." (PMID 35204228, 2022). "Besides, combination effects of PON1-L55M gene polymorphism and some oxidative stress markers such as total antioxidant capacity, malondialdehyde with breast cancer could be useful." (PMID 31983193, 2020). "Still, we were among the first to assess the influence of genetic variability of several antioxidative genes on cardiotoxicity of breast cancer treatment and the first to show that especially PON1 polymorphisms could contribute to the occurrence of cardiac adverse events." (PMID 33425072, 2020). "Furthermore, breast cancer becomes more susceptible to genomic damage as a result of lower levels of PON1 which could decrease the ability to detoxify inflammatory oxidants and dietary carcinogens." (PMID 31467900, 2019). "Epidemiological studies have revealed a relationship between PON1 polymorphisms implicated in the different types of cancer development and reduction in serum PON1 activities, such as lung, colorectal, prostate, and breast cancer, among others." (PMID 35453382, 2022). "The antioxidative-enzyme-encoding genes paraoxonase 1 (PON1), glutathione-S-transferases (GSTs), and catalase (CAT) stood out in a retrospective series of 101 patients with HER2-positive breast cancer that received adjuvant trastuzumab." (PMID 36230587, 2022). "In this meta-analysis, the associations of polymorphisms within paraoxonase 1 (PON1), leptin (LEP) and leptin receptor (LEPR) genes with susceptibility to breast cancer were comprehensively evaluated." (PMID 34452542, 2021).
breast carcinoma (continued). "In summary, this meta-analysis aimed to summarize association between the PON1 rs662, rs854560 LEP rs7799039 and LEPR rs1137101 polymorphisms and susceptibility to breast cancer." (PMID 34452542, 2021). "Our meta-analysis supports the growing body of evidence that the PON1 rs662 and rs854560 polymorphisms is emerging as a RISK factor for breast cancer." (PMID 34452542, 2021). "Paraoxonase 1 (PON1), leptin (LEP) and leptin receptor (LEPR) genes are good example of a GWAS-identified locus that has been implicated in development of breast cancer." (PMID 34452542, 2021). "In breast cancer patients treated with adjuvant RT, PON1 concentration and activity increased after RT with significant differences observed among different molecular subtypes." (PMID 33425072, 2020). "Studies suggest serum PON1 level and its activity are lower in cancer patients, including breast cancer, but only a few studies investigated the role of PON1 in cancer treatment response or toxicity." (PMID 33425072, 2020). "Our results suggest that PON1 genetic variability was the most important predictor of treatment-related cardiotoxicity in HER2-positive early breast cancer patients." (PMID 33425072, 2020). "Thus, we can obtain that PON1 (Q192R and L55M) gene polymorphisms play a vital role in the development of breast cancer, whose mechanism maybe as follows: there was a critical association between L allele and higher PON1 serum concentrations while M variant decreased the stability of this enzyme." (PMID 31467900, 2019). "The impact of PON1 on iDFS in women with early-stage breast cancer is described for the first time." (PMID 39519412, 2024). "In this regard, some studies have reported low expression and activity of PON1 (PONase, AREase, LACase) in patients with different types cancer such as cancer blander, gastrointestinal cancer, breast cancer, prostate cancer, lung cancer, non-Hodgkin lymphoma, and central nervous system tumors." (PMID 35453382, 2022). "Pooled data showed that PON1 rs662 and rs854560 polymorphisms were associated with risk of breast cancer in overall population, but not LEP rs7799039 and LEPR rs1137101." (PMID 34452542, 2021). "All previous meta-analysis have indicated that PON1 rs662 was associated with risk of breast cancer, but not rs854560." (PMID 34452542, 2021). "Thus, we performed a systematic review and updated meta-analysis to obtain a more precise assessment of the association between PON1, LEP and LEPR polymorphisms and the risk of breast cancer." (PMID 34452542, 2021). "Over the past decade, several molecular epidemiological studies have been performed to identify the association of PON1 rs662, rs854560, LEP rs7799039G>A, and LEPR rs1137101 polymorphisms with susceptibility to breast cancer, but the findings have been conflicting." (PMID 34452542, 2021). "PON1 was found to be a potential marker of survival in patients with breast cancer recurrence." (PMID 32076459, 2020). "For example, paraoxonase 1, overexpression of which had hitherto not been associated with breast cancer, has been mainly studied for its beneficial effect in organophosphate poisoning." (PMID 21711799, 2011). "However, they have not found any positive association between PON1 rs662 polymorphism and breast cancer in polled analyses." (PMID 34452542, 2021). "One metaanalysis reported significantly lower PON1 and ARE activities, in addition to serum HDL cholesterol, in patients with endometrium cancer, breast cancer, colorectal cancer, ovarian cancer, and stomach cancer." (PMID 32549522, 2020).
chronic kidney disease (30 papers, 2010 to 2025). Impairment of the renal function secondary to chronic kidney damage persisting for three or more months. "PON-1 enzymatic activity is associated with an intensity of kidney filtration: lower in patients with chronic kidney disease and hemodialysis." (PMID 37511134, 2023). "Clinical studies have demonstrated an association between diminished PON-1 and the progression of chronic kidney disease (CKD)." (PMID 35624764, 2022). "The rs662 AA genotype was linked with an unfavorable lipid profile and the lowest PON1 activity in patients with chronic kidney disease." (PMID 25155309, 2016). "In addition, evidence proposes a possible role for PON-1 in potentiating CVD associated with chronic kidney disease." (PMID 36140402, 2022). "Chronic kidney disease is associated with PON1 deficiency and hyperhomocysteinemia." (PMID 32967340, 2020). "Although promising as a biomarker for chronic kidney disease (CKD) progression, the diagnostic utility of PON1 requires further validation in larger, well-characterized patient cohorts." (PMID 40868959, 2025). "Deficiencies in PON-1 activity result in oxidative stress and detrimental clinical outcomes in the context of chronic kidney disease (CKD)." (PMID 36140402, 2022). "In this review, we summarize current evidence regarding PON1, emphasizing the importance of PON1 activity in chronic kidney disease." (PMID 38982880, 2024). "It has been shown that erythropoietin β and iron treatment has a beneficial effect on the levels of antibodies against oxidized LDL and on serum PON1 activity in pre dialysis patients with chronic renal disease and anemia." (PMID 38982880, 2024). "Experimentally, PON-1 not only has cardioprotective roles in chronic kidney disease, but also renal anti-inflammatory and anti-fibrotic roles in the setting of chronic hypertension and renal ischemia." (PMID 37108044, 2023). "Futurę studies incorporating the PON1 status are warranted in establishing PON1 relationships in end-stage renal disease patients treated with HD." (PMID 33762698, 2021). "An increase of oxidative stress and decrease of PON1 activity were reported in children with chronic renal failure." (PMID 24693505, 2013). "PON1 activity was lower in patients with renal insufficiency (chronic renal failure; chronic hemodialysis; chronic peritoneal dialysis) than in control subjects." (PMID 22523692, 2012). "Several studies have shown decreased levels of PON1 in chronic renal failure (CRF) patients, particularly those on hemodialysis." (PMID 20535264, 2010). "Clinically, PON-1 has well-known cardioprotective roles in patients with stable coronary artery disease, systolic heart failure, stable chronic heart failure, and chronic kidney disease." (PMID 37108044, 2023). "PON1 concentration and activity are lower in patients with chronic renal failure and in patients under renal replacement therapy as compared to healthy subjects whereas the effect of renal transplantation on PON1 activity remains unclear." (PMID 29333213, 2017). "The effects of treatment of anemia with exogenous recombinant erythropoietin (EPO) beta and iron on levels of antibodies against oxidized low-density lipoproteins as well as on serum PON1 activity and concentration were studied in 49 predialysis patients with chronic renal disease." (PMID 22523692, 2012). "We sought to determine the prognostic value of serum PON‐1 activity, as monitored by PON or arylesterase activities, in subjects with chronic kidney disease (CKD), particularly in relation to established cardiac biomarkers." (PMID 23557751, 2013). "However, an analysis of the earlier studies shows that significant changes in the activity of PON-1 and MPO appear most often in the end stages of chronic kidney disease, which may explain the lack of significance in our moderately advanced group of patients with CKD." (PMID 30857306, 2019).